VIP (vasoactive intestinal peptide)
Diseases named in the same sentence as VIP in open-access papers (continued):
Sharing a sentence is not in itself a finding about the gene and the disease.
infection (continued). "Importantly, SNV previously shown to have an increased stability compared to VIP, showed here significant trans-epithelial penetration and a clean toxicological profile, presenting a novel drug candidate that could be applied topically to counter both aseptic and infection-related bone destruction." (PMID 34025407, 2021). "In order to determine whether the decrease in Ly6C+ MDSCs in VIP−/− mice was due to differences in bone marrow production, we characterized the MDSC populations in the bone marrow 4 days after infection by flow cytometry." (PMID 29137229, 2017). "VIP-treatment lowered the percentage of Treg cells in spleens compared with PBS-treated WT mice following mCMV infection, while significantly decreasing levels of serum VEGF induced by mCMV-infection." (PMID 23723978, 2013). "It is important to consider that the pseudovirus only exerts one replication cycle, thus only allowing for investigation of the effects of VIP on virus entry by reduced surface receptor expression but not the possible suppression of the spread of infection by inhibiting viral replication." (PMID 40141308, 2025). "Although our results indicate that VIP i.p. injection is not a promising treatment for infection, we can thus not exclude that a more local treatment, for example restoring VIP in the epithelial cells only, may be more functional." (PMID 30252907, 2018). "Complex II-III activity was not affected by infection, cytokines or VIP." (PMID 30252907, 2018). "Therefore, VIP and PACAP may modulate the HIV-1 replication by controlling the availability of essential components for the establishment of a productive infection." (PMID 29951068, 2018). "VIPhyb-treated and VIP-KO mice had less inflammation and tissue damage in the liver, with fewer intranuclear viral inclusions, fewer inflammatory leukocytes, less necrosis, and fewer CMV-infected giant cells for 3–10 days after mCMV infection compared with PBS-treated WT mice." (PMID 23723978, 2013). "Thus, therapeutic VIP administration to restore the decreased levels during infection had beneficial effects on epithelial cells and their mitochondria, but not on the overall infection outcome." (PMID 30252907, 2018). "First, we observed that in the absence of a functional VIP/VPAC2 axis, the classical Bordetellae fail to colonize the lungs with low infection dosages and infection is more rapidly clear from the lower respiratory tract." (PMID 37065208, 2023). "VIP (10 nM) alleviated the NO2- generation induced by IFNγ and TNFα with and without infection (p<0.001)." (PMID 30252907, 2018). "VIP-KO mice and VIPhyb-treated WT mice had similar histological evidence for hepatocyte regeneration at 10 days post-infection as PBS-treated WT mice, indicating that VIP signaling is not necessary for tissue repair after mCMV infection." (PMID 23723978, 2013). "We have not evaluated the role of VIP/VPAC2 in the generation of protective immunity or its impact in the Th1/Th17 and Th2 responses, though it is clear that it has an impact on the length of infection, which should be further investigated." (PMID 37065208, 2023).
neurodegenerative disease (12 papers, 2012 to 2024). A disorder of the central nervous system characterized by gradual and progressive loss of neural tissue and neurologic function. "Neuroinflammation may be a pathogenic mechanism common to several neurodegenerative diseases, so VIP may be widely applicable as a neuroprotective agent by suppressing the pathological activities of activated microglia." (PMID 22328918, 2012). "The beneficial effects of PACAP and VIP on cognitive disturbances that occur in neurodegenerative diseases are due to the expression of their receptors in affected brain areas." (PMID 32765225, 2020). "Currently, it is considered that in the context of neurodegenerative diseases, the VIP-VPACR system exerts its neuroprotective action mainly indirectly through astroglial and microglial cells." (PMID 32765225, 2020). "This action of VIP on microglial cells has been studied in neurodegenerative diseases, as excessive microglial activation contributes to the physiopathology of AD, PD, and HD, among others." (PMID 32765225, 2020). "In the setting of neurodegenerative diseases, VIP and VIP-based analogs downregulate microglia pro-inflammatory activities and spare dopaminergic neuronal damage in the nigra and striatum." (PMID 31619964, 2019). "Recently, a lot of reports have focused on the role of VIP and its receptors in chronic inflammation and neurodegenerative diseases." (PMID 23162538, 2012). "This context and the capacity of PACAP and VIP to cross the blood-brain barrier suggest that these neuropeptides and their receptors-mediated signaling could have promising therapeutic activity in neurodegenerative diseases." (PMID 32765225, 2020). "Thus, understanding the dysregulation of the PACAP/VIP neuropeptide system in chronic neuroinflammation may pave the way for the development of novel therapeutic strategies for the treatment of MS and/or other relevant neurodegenerative diseases." (PMID 39273398, 2024). "Beneficial effects of pituitary adenylate cyclase-activating polypeptide (PACAP) and vasoactive intestinal peptide (VIP) in cellular and animal models of different neurodegenerative diseases." (PMID 32765225, 2020). "Although some authors have found VIP direct effect in neurons, there is increasing evidence that most neuroprotective actions promoted by VPAC receptors in neurodegenerative diseases involve glial cells." (PMID 32765225, 2020). "Vasoactive intestinal peptide (VIP) also activates these receptors, and this close analogue of PACAP has also shown to promote neuronal survival in various animal models of acute and progressive neurodegenerative diseases." (PMID 35237767, 2022). "Finally, we review novel VIP and PACAP synthetic derivatives which could represent promising therapeutic tools for the treatment of neurodegenerative diseases." (PMID 32765225, 2020).
immune disease (6 papers, 2014 to 2023). "Because all three conditions represent diseases of the immune system that share an ‘infectious trigger’, we asked if the ViP/sViP signatures are also induced in the setting of other diseases of the immune system." (PMID 35577777, 2022). "Highlighting the relevance of endogenous VIP production, VIP knockout (KO) mice exhibit a wide variety of immune disorders." (PMID 31969877, 2019). "The VIP is a well-characterized endogenous anti-inflammatory neuropeptide with therapeutic potential for a variety of immune disorders." (PMID 25101851, 2014). "VIP is an important signal molecule of the neuroendocrine-immune network, and a well characterized endogenous anti-inflammatory neuropeptide with therapeutic potential for a variety of immune disorders." (PMID 25101851, 2014).
inflammation (6 papers, 2011 to 2022). Aberrant reaction of the microcirculation characterized by movement of fluid and leukocytes from the blood into extravascular tissues. "GLP2 has further been found to attenuate inflammation-induced intestinal damage and levels of proinflammatory cytokines in animal models of intestinal inflammation via release of VIP." (PMID 22463807, 2012). "Under physiological conditions, VIP is mainly cleaved by endopeptidase, whereas in states of airway inflammation, mast cell enzymes dominate the degradation of VIP." (PMID 21477377, 2011). "Since VIP shows neuroprotective properties, controls the immune reactions and plays a key role during inflammatory processes, the possibility of the use of VIP analogs as drugs during intestinal inflammations has been tested in recent years." (PMID 32998326, 2020). "Moreover, significant correlations between the VIP levels in the serum and the severity of intestinal inflammation have been also observed, which suggests that the testing of VIP levels may be one of the diagnostic factors during gastrointestinal diseases." (PMID 32998326, 2020). "We also examined the effects of transient neonatal gastric inflammation on ghrelin, CCK and VIP expressions; the brain–gut axis response to stress; and the mechanism of XSLJZD on FD." (PMID 26508134, 2015). "These molecules may also be involved in the development of neurogenic inflammation, where active nociceptors release neurotransmitters (i.e., substance P, SP, calcitonin gene-related peptide, CGRP, vasoactive intestinal peptide, VIP) from peripheral terminals." (PMID 35326422, 2022).
neurodevelopmental disorder (6 papers, 2020 to 2025). A behavioral and cognitive disorder with onset during the developmental period that involves impaired or aberrant development of intellectual, motor, or social functions. "Despite dysfunctional vasoactive intestinal polypeptide‐positive interneurons (VIP‐INs) being linked to the emergence of neurodevelopmental disorders, the temporal profile of VIP‐IN functional maturation and cortical network integration remains unclear." (PMID 39803724, 2025). "Recent work has suggested that vasoactive intestinal peptide-expressing (VIP) interneurons may play a critical role in the proper development and function of cortical circuits, making them a potential key point of vulnerability in neurodevelopmental disorders." (PMID 32343226, 2020).
bacterial infection (5 papers, 2021 to 2026). "Most recently, studies in the 2020s provide a nuanced view of how VIP suppresses inflammatory damage but also enables pathogen persistence during live bacterial infection, implicating VIP signaling in trade-offs between tolerance and clearance." (PMID 42117802, 2026). "Mechanistically, during bacterial infection, sensory neurons preferentially release vasoactive intestinal polypeptide (VIP)." (PMID 39414787, 2024). "While the regulation of On-VIP on the MyD88 pathway was specific to tissues after bacterial infection, thus promoting its expression in the intestine and spleen and inhibiting its expression in the liver and brain." (PMID 36499231, 2022). "The regulatory activities and mechanisms of VIP in the immune response of teleost against bacterial infection were initially investigated." (PMID 36499231, 2022). "In the bacterial infection model (LPS), SNV significantly reduced IL1β expression, while VIP increased IL6 expression." (PMID 34025407, 2021). "To determine the effects of btrS on the manipulation of VIP/VPAC2 signaling, we evaluated the differences between murine bacterial infection by using the calculated ID50 values following inoculation with the wildtype BbRB50 strain, a mutant RB50 strain lacking the sigma factor btrS (RB50ΔbtrS)." (PMID 37065208, 2023). "The transcriptional levels of P65 in the On-VIP + S. agalactiae group showed a significant downregulation (p < 0.05) from 6 h to 48 h post-challenge in the brain, head kidney, intestine, liver, and spleen, compared to the PBS + S. agalactiae group during bacterial infection." (PMID 36499231, 2022). "In this study, the VIP precursor gene (On-VIP) and its receptor gene VIPR1 (On-VIPR1) were identified from Nile tilapia (Oreochromis niloticus), and the functions of On-VIP in the immunomodulation of Nile tilapia against bacterial infection were investigated and characterized." (PMID 36499231, 2022).
psychiatric disorder (5 papers, 2020 to 2024). A disorder characterized by behavioral and/or psychological abnormalities, often accompanied by physical symptoms. "The implications of interneuronal dysfunction are profound, as evidenced by the association of VIP+ interneurons with various neurological and psychiatric disorders." (PMID 39916937, 2024). "However, somatostatin-expressing (SST+) and vasoactive peptide-expressing (VIP+) interneurons contribute substantially to regulating GABAergic inhibition in the cortex and dysfunction of these interneurons are associated with psychiatric disorders." (PMID 35185505, 2022). "Genetically defined interneuron groups, such as PV, SOM and VIP, and their connectivity motifs have profoundly advanced understanding of cortical computation and psychiatric disorders." (PMID 37474640, 2023). "Lymphocytes from patients with these mutations exhibited higher VIPR2 gene expression and VIP-induced cAMP responsiveness, but mechanisms by which overactive VPAC2 signaling may lead to these psychiatric disorders are unknown." (PMID 32581681, 2020).
neurological disorders (4 papers, 2018 to 2024). "Accumulating evidence suggests that altered PACAP and VIP signals can be a risk factor for psychiatric and neurological disorders such as schizophrenia and stress-related disorders." (PMID 29734363, 2018). "The present review holds notable significance in shedding light on the critical role of PACAP in comparison with other neuropeptides like CGRP and VIP, which have been extensively studied as potential therapeutic targets for various neurological disorders." (PMID 37998384, 2023). "Because PACAP and VIP signals might be related to psychiatric and neurological disorders, the present observations as well as the assay systems generated are expected to contribute to therapeutic drug development." (PMID 29734363, 2018).
digestive system diseases (3 papers, 2018 to 2023). "However, due to the short half-life and fast metabolism of VIP in vivo, and because the long-term injection of VIP will cause immune suppression and gastrointestinal disorders, the clinical application of VIP is greatly restricted." (PMID 29540226, 2018). "In terms of promoting gastrointestinal motility, acupuncture takes effect by regulating the level of the vasoactive intestinal peptide in digestive system diseases." (PMID 33029166, 2020). "VIP has a short half-life and fast metabolism in vivo, and the long-term injection of VIP will produce immune suppression and gastrointestinal disorders." (PMID 29540226, 2018).
gastrointestinal disease (3 papers, 2018 to 2020). A disease that occurs in the gastrointestinal system, excluding the hepatobiliary system. "The change of GAS, MTL, and VIP levels are closely related to gastrointestinal diseases." (PMID 31949463, 2019).
infectious disease (3 papers, 2017 to 2022). A disorder directly resulting from the presence and activity of a microbial, viral, or parasitic agent in humans. "In contrast to SP, administration of VIP has been shown to act beneficially in the course of the variety of infectious disorders, mainly by extinguishing inflammatory reactions." (PMID 33915818, 2021). "A notable exception is, however, VIP which has proved to be successful in murine models of certain infectious diseases." (PMID 33915818, 2021). "In the case of infectious diseases, and more specifically CMV infection, little is known about the effect of VIP on CD11b+ GR-1+ cells." (PMID 29137229, 2017).
metabolic disorders (3 papers, 2023 to 2024). "The pituitary adenylate cyclase-activating polypeptide (PACAP)-selective PAC1 receptor (PAC1R) is a member of the vasoactive intestinal peptide (VIP)/secretin/glucagon family of G protein-coupled receptors (GPCRs), which play important roles in metabolic disorders." (PMID 39195547, 2024). "Further characterization of how dietary perturbations affect the activity of VIP-producing neurons might reveal new therapeutic approaches for the modulation of metabolic disorders." (PMID 39761015, 2024).
cardiovascular disease (2 papers, 2021 to 2022). "In addition, VIP levels are reduced in PD, and these patients may have an increased risk of cardiovascular disease." (PMID 34566619, 2021).
dermatitis (2 papers, 2009 to 2023). An inflammatory process affecting the skin. "VIP differentially regulates immune functions according to the tissue and the disease, and its role in skin disorders has yet to be detailed." (PMID 19668696, 2009). "Since VIP is involved in many pathophysiological processes, its release suggests a putative regulatory role for MCs in skin disorders." (PMID 19668696, 2009).
Intestinal Disease (2 papers, 2013 to 2020). "It should be noted that previous studies have reported changes in the expression of VIP in the digestive tract during various intestinal diseases." (PMID 32998326, 2020).
benign tumors (1 paper, 2022). "VPAC1 receptors (a combined for vasoactive intestinal peptide (VIP) and PACAP) are minimally expressed in normal cells and benign tumors but expressed in high density on many types of malignant cells." (PMID 36359312, 2022).
brain disorder (1 paper, 2022). A disease affecting the brain or part of the brain. "Subgenual anterior cingulate cortex (sgACC) of human subjects without brain disorders were labeled using fluorescent in situ hybridization (FISH) for CRH and markers of excitatory (SLC17A7), inhibitory (GAD1) neurons, as well as markers of other interneuron subpopulations (PVALB, SST, VIP)." (PMID 35280164, 2022).
electrolyte imbalance (1 paper, 2010). "Recently, have been described nine cases of VIP-oma in which octreotide was very successful as adjuvant therapy for symptoms control and for reducing the serum elevated VIP levels improving the diarrhoea and the electrolyte imbalance." (PMID 20196864, 2010).
peripheral neuropathies (1 paper, 2019). "Thus, further investigation of VIP and PACAP immunomodulatory function on CMT mouse models could potentially develop VIP and PACAP as novel molecules for the treatment of peripheral neuropathies." (PMID 31920495, 2019).
VIP also shares sentences with these, for which no sentence is quoted: autism (5 papers); Insulin resistance (5); lupus (4); Allergy (3); anemia (3); endometritis (3); headache disorder (3); pheochromocytomas (3); rhinitis (3); Ataxia (2); Cerebral ischemia (2); eosinophilia (2); ganglioneuroblastoma (2); lymphoma (2); Miosis (2); Myocardial fibrosis (2); osteoporosis (2); ptosis (2); rhinosinusitis (2); Spondyloarthritis (2); vasculitis (2); Zollinger-Ellison syndrome (2); Acidosis (1); acute endometritis (1); acute myocardial infarction (1); acute pancreatitis (1); acute respiratory distress syndrome (1); adenosquamous cell carcinoma (1); alopecia areata (1); atherosclerosis (1).
A further 93 diseases each share a sentence with VIP in 1 paper.